P2RY2 (purinergic receptor P2Y2)
Diseases named in the same sentence as P2RY2 in open-access papers:
P2RY2 is named in the same sentence as 135 diseases in open-access papers, as found by Europe PMC text mining. Sharing a sentence is not in itself a finding about the gene and the disease. The quoted sentences say what the papers report.
breast cancer (25 papers, 2011 to 2025). A primary or metastatic malignant neoplasm involving the breast. "The P2RY2 enhancer RNA (P2RY2e) has been validated as an estrogen-responsive eRNA and has been involved in the development of breast cancer and the progression of bladder cancer." (PMID 37584707, 2023). "In addition, similar results were shown in mammary tumor experiments at P2RY2, indicating that P2RY2 most likely regulates tumor cells' migration and invasion process by regulating the expression of cell adhesion-related genes Snail and E-calmodulin." (PMID 38180750, 2024).
prostate carcinoma (9 papers, 2014 to 2023). A carcinoma that arises from epithelial cells of the prostate gland. "Previous reports demonstrated that extracellular ATP activates P2RY2 and promotes prostate cancer cells invasion and metastasis." (PMID 31159832, 2019).
pulmonary fibrosis (8 papers, 2017 to 2025). Chronic progressive interstitial lung disorder characterized by the replacement of the lung tissue by connective tissue, leading to progressive dyspnea, respiratory failure, or right heart failure. "In this manuscript we investigated the involvement of extracellular nucleotides and the purinergic receptor P2Y2 in the pathogenesis of idiopathic pulmonary fibrosis in humans and in the animal model of bleomycin induced lung fibrosis." (PMID 28415591, 2017).
ovarian carcinoma (7 papers, 2017 to 2023). A malignant neoplasm originating from the surface ovarian epithelium. "In particular, KCa3.1 blockade or downregulation in Skov-3 human ovarian cancer cells prevented ATP-induced cell migration possibly due to a loss of interaction between KCa3.1 and the purinergic receptor P2Y2." (PMID 30658505, 2019).
asthma (6 papers, 2016 to 2024). "Our investigations concerning bone-marrow-derived cells from hematopoietic origin support our former findings demonstrating that P2RY2 is crucial for migration and maintenance of asthma by recruitment of dendritic cells." (PMID 37790940, 2023). "This provides new insights into the asthma pathogenesis and offers new possibilities regarding a cell-specific therapy of allergic asthma by P2RY2-targeted medication." (PMID 37790940, 2023). "Therefore, P2RY2 antagonists are now also being considered as a therapeutic option, for example for the treatment of inflammatory respiratory diseases such as asthma or COPD." (PMID 37790940, 2023).
glioma (6 papers, 2009 to 2025). A benign or malignant brain and spinal cord tumor that arises from glial cells (astrocytes, oligodendrocytes, ependymal cells). "In glioma, elevated P2RY2 expression enhances tumor invasiveness and is associated with poor prognosis, suggesting its potential as a prognostic biomarker and therapeutic target." (PMID 41331166, 2025). "Notably, nine core MicT/MicN genes displayed closely associations with glioma recurrence and prognosis, such as P2RY2, which was analyzed in more than 2800 glioma samples from 25 studies." (PMID 35729639, 2022).
Insulin resistance (6 papers, 2020 to 2023). Increased resistance towards insulin, that is, diminished effectiveness of insulin in reducing blood glucose levels. "Based on the description above, the differential expression of P2RY2 in liver cells may contribute to the insulin resistance." (PMID 32382544, 2020). "Thus, APOAV overexpression may prevent the insulin resistance in liver cells by mediating the genes such as AGTR1 and P2RY2." (PMID 32382544, 2020).
chronic obstructive pulmonary disease (5 papers, 2014 to 2024). A chronic and progressive lung disorder characterized by the loss of elasticity of the bronchial tree and the air sacs, destruction of the air sacs wall, thickening of the bronchial wall, and mucous accumulation in the bronchial tree. "Our observation is in line with the previous findings showing higher expression levels of P2ry2 in chronic obstructive pulmonary disease (COPD) patients and the role of P2Y2 receptor in chemotaxis of dendritic cells and eosinophils in allergic lung inflammation." (PMID 38179047, 2023).
gastric cancer (5 papers, 2015 to 2023). A primary or metastatic malignant neoplasm involving the stomach. "cDNA microarray analysis showed higher expression of P2RY2 transcript in gastric cancer biopsies than adjacent healthy tissue." (PMID 36741002, 2023). "One study also showed by cDNA microarray analysis that the P2RY2 transcript is highly expressed in fresh biopsies of gastric cancer tissue, compared to adjacent healthy tissue." (PMID 32635260, 2020). "Of note, increased P2RY2 mRNA levels have also been detected in gastric cancer biopsies from 14 patients (as compared to the adjacent healthy mucosa), but these findings do not allow to determine whether gastric neoplasms were infiltrated by P2RY2+ immune cells or whether they overexpressed P2RY2." (PMID 26300886, 2015). "P2RY2, Ephbl and CD248 were explored for gastric cancer detection." (PMID 30847027, 2019). "Genes highly expressed in gastric cancer were CD248, NSDl, RABl7, ABCG8, Ephbl and P2RY2." (PMID 30847027, 2019).
Hypertension (5 papers, 2020 to 2024). The presence of chronic increased pressure in the systemic arterial system. "Activation of P2ry2 specifically in principal cells lowers blood pressure in the DOCA-salt model of hypertension." (PMID 37279066, 2023). "Consequently, principal cell–specific KO of P2ry2 prevents decreases in blood pressure in response to P2Y2 receptor stimulation in the DOCA-salt model of hypertension." (PMID 37279066, 2023). "Consequently, principal cell–specific knockout of P2ry2 prevented decreases in blood pressure in response to P2ry2 stimulation in the deoxycorticosterone acetate–salt (DOCA-salt) model of hypertension." (PMID 37279066, 2023). "We report here that the chemically distinct P2ry2 agonist, MRS2768, drives a natriuresis in mice maintained with a sodium-free diet and decreases blood pressure in the DOCA-salt model of hypertension." (PMID 37279066, 2023).
fibrosis (3 papers, 2017 to 2024). the formation of excess fibrous connective tissue in an organ or tissue in a reparative or reactive process. "Fibrosis is a complex pathological process that can lead to the permanent loss of biological function, with P2ry2 playing a crucial role in this process." (PMID 39133718, 2024).
ischemia (3 papers, 2022 to 2025). A hypoperfusion of the BLOOD through an organ or tissue caused by a PATHOLOGIC CONSTRICTION or obstruction of its BLOOD VESSELS, or an absence of BLOOD CIRCULATION. "Our results support a potentially unique involvement of P2RY2 in recovery from ischemia." (PMID 35887219, 2022).
pancreatic ductal adenocarcinoma (3 papers, 2021). An infiltrating adenocarcinoma that arises from the epithelial cells of the pancreas. "Accordingly, recent studies have demonstrated that P2RY2 expression was elevated in pancreatic ductal adenocarcinoma and in head and neck squamous cell carcinoma (HNSCC), and its inhibition suppressed cancer cell growth both in vitro and in vivo." (PMID 34768902, 2021). "A recent study demonstrated that activated Purinergic Receptor P2Y2 (P2RY2) contributed to the activation of the PI3K-mTOR pathway thus enhancing cancer glycolysis in pancreatic ductal adenocarcinoma." (PMID 33791391, 2021). "P2RY2 overexpression has been shown in biopsies originating from breast and gastric cancer, pancreatic ductal adenocarcinoma as well as of basal cell and squamous cell carcinomas." (PMID 34768902, 2021).
Sepsis (3 papers, 2014 to 2025). Sepsis is defined as life-threatening organ dysfunction caused by a dysregulated host response to infection. "P2RY2 has been shown to play a role in neutrophil chemotaxis in a mouse model and is also involved in the recruitment of PMNs to the lung resulting in acute lung injury in sepsis." (PMID 24612859, 2014).
status epilepticus (3 papers, 2018 to 2021). Status epilepticus is defined as a continuous seizure lasting more than 30 min, or two or more seizures without full recovery of consciousness between any of them. "Both, intraamygdala KA and intraperitoneal pilocarpine-induced status epilepticus increased the transcription of the uridine-sensitive P2Y receptors P2ry2, P2ry4, and P2ry6 in the hippocampus." (PMID 29563872, 2018). "Status epilepticus: Increased P2ry2, P2ry4, and P2ry6 and decreased P2ry1, P2ry12, P2ry13, and P2ry14 transcript levels; increased P2Y1, P2Y2, P2Y4, and P2Y6 and decreased P2Y12 protein levels." (PMID 29563872, 2018). "Analysis of the hippocampus 14 days-post status epilepticus revealed increased P2ry1, P2ry2, and P2ry6 transcription and increased P2Y1, P2Y2, and P2Y12 protein levels." (PMID 29563872, 2018).
acute myeloid leukemia (2 papers, 2021 to 2025). Acute myeloid leukemia (AML) is a group of neoplasms arising from precursor cells committed to the myeloid cell-line differentiation. "Finally, activation of P2RY2-AKT signaling has been shown to promote leukemogenesis in acute myeloid leukemia." (PMID 41168841, 2025). "Comparing with other cancer types, glioblastoma multiforme and acute myeloid leukemia showed a significant upregulation of P2RY1 and P2RY2, respectively, compared to their normal tissues, and conversely, the low expression of the genes provided more advantage in the overall patient survival." (PMID 34833046, 2021).
allergic asthma (2 papers, 2022 to 2023). A asthma with a basis in a pathological type I hypersensitivity reaction. "Among the G-protein-coupled seven-transmembrane P2Y receptors is P2RY2, which has been implicated in the pathogenesis of various inflammatory disorders including allergic asthma by promoting inflammatory cell recruitment." (PMID 37790940, 2023). "The present work contributes to a better understanding of cells that mediate proinflammatory effects in allergic asthma via P2RY2 signaling." (PMID 37790940, 2023).
bladder cancer (2 papers, 2022 to 2023). "Among the purinergic receptors that are activated by ATP, P2RY2 could regulates cell proliferation in various tumors, such as lung and bladder cancer." (PMID 35729639, 2022).
dyslipidemia (2 papers, 2021). "Activation of the purinergic receptor P2Y2R has been reported to promote adipogenesis, inflammation and dyslipidemia in adipose tissues in obese mice." (PMID 34073834, 2021).
endometrial carcinoma (2 papers, 2002 to 2022). A malignant tumor arising from the epithelium that lines the cavity of the uterine body. "In the immunohistochemical staining results of endometrial cancer tissues, we also found that the expression of P2RY2 was higher in tumor tissues." (PMID 36207698, 2022). "The result suggested that P2RY2 could promote tumor proliferation, which was consistent with our previous inference on the role of IRGs in endometrial cancer." (PMID 36207698, 2022). "Thus, we verified the expression of P2RY2 in endometrial cancer tissues and its effect on the growth of endometrial cancer cells primarily." (PMID 36207698, 2022). "Eight IRGs were incorporated to construct a nomogram for survival prediction in endometrial carcinoma patients, including CCR7, GNA15, GPR132, LTA, MYC, NOD2, P2RX4 and P2RY2." (PMID 36207698, 2022).
lung carcinoma (2 papers, 2020 to 2021). "Next, we determined the expression levels of P2X sub-families P2RX1–7 and P2Y receptors P2RY1, P2RY2, P2RY4, P2RY5 (LPAR6), P2RY6, P2RY7 (LTB4R), P2RY8, P2RY9 (LPAR4), P2RY10–14 in normal lung tissues and lung cancer tissues." (PMID 32638267, 2020).
uveitis (2 papers, 2015 to 2025). An inflammatory process affecting a part of or the entire uvea. "Some of the genes that were identified as important classifiers of the uveitis only group, such as P2RY2 and CCR2, are known to be relevant in the pathogenesis of uveitis." (PMID 40270958, 2025).
eosinophilia (1 paper, 2023). "We found that knockout of P2ry2 in these models resulted in reduced BALF eosinophilia, attenuated type 2 cytokine production of HDM re-stimulated MLN cells, decreased peribronchial inflammation, and reduced bronchial hyperreactivity in response to increasing doses of nebulized methacholine." (PMID 37790940, 2023).
kidney cancer (1 paper, 2024). Primary or metastatic malignant neoplasm involving the kidney. "P2RY2, P2RY6, and P2RY11 are three Purinergic genes that we believe are closely related to KIRC but are currently less studied about kidney cancer." (PMID 38180750, 2024).
tumor (52 papers, 2007 to 2025). "In contrast, expression of genes correlated with worse survival and hypoxia (PANX1, NT5E, ADORA2B, and P2RY2) was associated with tumor cells and the squamous PDAC subtype, correlating with hypoxia, inflammation, and worse prognosis." (PMID 36942939, 2023). "Purinergic receptor P2Y2 (P2RY2) activation has been reported to promote tumor cell proliferation via multiple downstream signaling pathways." (PMID 37584707, 2023). "Taking P2RY2 as an example, RT-PCR results showed that the expression level in the tumor was significantly higher than that in the adjacent tumor." (PMID 36207698, 2022). "Accumulation of ATP in the extracellular medium can be sensed by purinergic receptor P2Y2, which is important for the recruitment of CD11b + CD11c + Ly6Chigh cells to the tumor microenvironment." (PMID 34599143, 2021). "The role of P2RY2, P2RY6, and P2RY12 receptors in gastrointestinal tumors has been reported, including involvement in tumor cell proliferation, metabolism, proliferation, apoptosis, and chemotherapy drug resistance." (PMID 34494914, 2021). "Studies from our group and others have demonstrated that tumor cells upregulate the P2 purinergic receptors P2RY1, P2RY2, P2RX3 and P2RX7 and utilize extracellular ATP to support tumor growth and metastasis." (PMID 33420030, 2021). "Quantification of the other subtypes confirmed that P2RY2, P2RY4 and P2RY14 were not significantly upregulated in the tumor samples compared to normal samples." (PMID 38773214, 2024).
cancer (37 papers, 2012 to 2025). A tumor composed of atypical neoplastic, often pleomorphic cells that invade other tissues. "Aberrant activation of P2RY2 has been implicated in several cancers by promoting proliferation, invasion, angiogenesis, and immune evasion." (PMID 41331166, 2025). "P2RY2 presents as the purinergic gene with the strongest association with hypoxia, the highest cancer cell-specific expression, and the strongest impact on overall survival." (PMID 36942939, 2023). "Extracellular ATP from cancer cells that undergo ICD mediates immune system chemotaxis by binding to purinergic receptor P2Y2 (P2RY2), and promoting the secretion of interleukin 1 β (IL-1β) and interleukin-18 (IL-18) by activating inflammatory corpuscles." (PMID 37153795, 2023). "P2RY2, encoding P2Y2 - a GPCR activated by ATP and UTP, was shown to be the purinergic gene most highly associated with cancer cell-specific expression in all our independent analyses." (PMID 36942939, 2023). "P2RY2 was reported to enhance cancer cell glycolysis by PI3K/AKT-mammalian target of rapamycin (mTOR) signaling, resulting in PAAD progression." (PMID 36428619, 2022). "Together, this makes it difficult to generalize a direct correlation between P2RY2 activation, Ca2+ mobilization, cAMP levels and cancer cell viability for CRC." (PMID 34768902, 2021). "The high expression of P2RY1 and P2RY2 conferred better overall survival benefit to the patients as the cancers resembled more ‘normal tissue’ receptor expression." (PMID 34833046, 2021). "ARIEL in leukemia, HPSE in different cancer types, and P2RY2 in bladder cancer are other examples of eRNAs targeted by knockdown approaches that may serve as new therapeutic targets for cancer treatment." (PMID 36287118, 2022). "Therefore, inhibiting P2RY2 in CRC might be either useless or counter-productive in terms of cancer cell survival." (PMID 34768902, 2021).
brain disorder (3 papers, 2021 to 2022). A disease affecting the brain or part of the brain. "Thus, the novel mechanisms of P2RY2 up-regulation and function in the nervous system warrant further investigation, providing new strategies for the treatment and management of corresponding brain diseases." (PMID 35729639, 2022).
inflammation (3 papers, 2023 to 2024). Aberrant reaction of the microcirculation characterized by movement of fluid and leukocytes from the blood into extravascular tissues. "Taken together, our findings clearly demonstrate that P2RY2 promotes HDM-induced airway inflammation by mediating proinflammatory cytokine production in airway epithelial cells, monocytes, and dendritic cells." (PMID 37790940, 2023). "Altogether, our results show that ATP-neutralization or blocking of P2RY2 attenuates LPS-induced lung inflammation." (PMID 38179047, 2023). "In summary, our results show that P2RY2 contributes to HDM-induced airway inflammation by mediating proinflammatory cytokine production in airway epithelial cells, monocytes, and dendritic cells and drives the recruitment of lung dendritic cells and monocytes." (PMID 37790940, 2023). "Here, we used conditional P2ry2 knockout expressing cre-recombinase in different cell types in an acute HDM-induced model of airway inflammation." (PMID 37790940, 2023). "Altogether, these data suggest that the P2RY2 in non-hematopoietic system is not involved in LPS-induced airway inflammation." (PMID 38179047, 2023).
P2RY2 also shares sentences with these, for which no sentence is quoted: atherosclerosis (17 papers); infection (14); dry eye (8); Obesity (7); cystic fibrosis (6); diabetes (6); hepatocellular carcinoma (6); astrocytoma (5); breast tumor (4); epilepsy (4); myocardial infarction (4); Alzheimer disease (3); cardiovascular diseases (3); chronic kidney disease (3); Hepatic steatosis (3); HIV-1 infection (3); idiopathic pulmonary fibrosis (3); pancreatic cancer (3); sialadenitis (3); acute kidney injury (2); adenocarcinoma (2); colitis (2); colon cancer (2); cutaneous leishmaniasis (2); cyst (2); endothelial dysfunction (2); gastric neoplasm (2); Hepatitis (2); liver disease (2); metabolic disease (2).
A further 77 diseases each share a sentence with P2RY2 in 2 papers or fewer.